TSC1 (TSC complex subunit 1)
Diseases named in the same sentence as TSC1 in open-access papers (continued):
Sharing a sentence is not in itself a finding about the gene and the disease.
breast carcinoma (31 papers, 2006 to 2025). "Further, the in vivo loss-of-function Cas9-sgRNA screening identified NF1, TSC1, and TβRII as critical mediators in repressing inflammatory responses and breast cancer metastasis." (PMID 38997291, 2024). "In contrast, according to the Cancer Genome Atlas data, the mutation rate of TSC1/TSC2 was only 0.7% (P = 0.0004) in patients with HR+/HER2- early-stage breast cancer." (PMID 37251941, 2023). "It is reported that low TSC1 expression level is associated with poor clinical outcomes of breast cancer and gastric cancer." (PMID 35572821, 2022). "We tested the IL-13 and TSC1 SNPs for replication of main effects by conducting lookups in genome-wide association study (GWAS) data from the Shanghai Breast Cancer Genetics Study (SBCGS)." (PMID 30601841, 2019). "Analyses across independent breast cancer datasets revealed associations between low TSC1/2 expression, altered mTOR complex 1 (mTORC1) pathway signaling, and metastasis to lung." (PMID 26167915, 2015). "Beyond the specific analysis of TSC1/2, a pathway-based analysis of the same breast cancer dataset suggested an association between mTORC1 activity and lung but not bone metastasis events." (PMID 26167915, 2015). "Having suggested an association between TSC1/2 expression and the lung metastatic potential of breast cancer, we performed immunohistochemistry studies of the lung metastasis mediators in paraffin-embedded lung tissue from 23 LAM patients." (PMID 26167915, 2015). "Collectively, these results suggest a specific link between loss of TSC1/2 expression—and probably, therefore, activated mTORC1 signaling—and lung metastatic potential in breast cancer." (PMID 26167915, 2015). "We also provide evidence that the TSC1 SNP rs7874234 may interact with physical activity to influence breast cancer risk." (PMID 30601841, 2019). "Notably, in breast cancer, relative low expression of hamartin and tuberin (TSC1 and TSC2 products, respectively) is associated with poor clinical outcome, and depletion of tuberin promotes metastasis." (PMID 26167915, 2015). "To further evaluate IPScan’s performance, we applied it to various mammalian cell types, including Tsc1−/− mouse embryonic fibroblasts (MEFs) and wild-type (WT) MEFs, as well as the human breast cancer cell lines MCF7 and BT549." (PMID 41218079, 2025). "The expression of several isoforms, such as AKT2 and TSC1, changes significantly across time, implicating these genes and their isoforms in breast cancer development and recurrence." (PMID 39888956, 2025). "Conversely, low levels of TSC1 and TSC2 are associated with an unfavorable prognosis in breast cancer and some other cancers." (PMID 39367202, 2024). "We further investigated the expression of NF1, TSC1, and TβRII in human breast cancer using the TCGA dataset." (PMID 38997291, 2024). "The expression of activated IKKbeta correlates with TSC1 Ser511 phosphorylation and VEGF production in breast cancer patients and is associated with poor prognosis in breast cancer." (PMID 37251941, 2023). "Some of the top hits identified by our screen, including PTEN, CSK, NF1, and TSC1/2 had previously been identified by a CRISPR-Cas9 screen that was performed with the ERα+ breast cancer cell lines MCF7 and T47D." (PMID 37172090, 2023). "The expression of CXXC5, CUL4B, and MTA1 increased during the occurrence and development of breast cancer, and correspondingly, TSC1 expression decreased." (PMID 36539038, 2023). "Correspondingly, immunohistochemical staining showed that the expression of TSC1 in breast carcinoma specimens was lower than that in normal tissues, and the expression level decreased with increasing tumor histological grade." (PMID 36539038, 2023). "We noticed that the number of exon inclusions varied among the profiled cellular models (60% in breast cancer transcriptome compared to 90% in Tsc1-/- MEF transcriptome)." (PMID 36293270, 2022).
breast carcinoma (continued). "The plots showed that the survival of breast cancer patients with reduced methylation of TSC1 (cg14350545), FADD (cg02794589), and TRADD (cg05178604) was significantly improved." (PMID 33194583, 2020). "It has been demonstrated in breast cancer cell lines that IKKβ is a TSC1 kinase whose activity leads to TSC1 suppression, mTOR activation and enhanced angiogenesis, favoring tumor development." (PMID 29292732, 2017). "Mutations in the PI3K/AKT/mTOR pathway are frequent in breast cancer, and activation of this pathway via molecular aberrations in PIK3CA, PIK3CB, PIK3R1, AKT, TSC1/2, and PTEN promotes resistance to HER2-targeted therapies." (PMID 27923043, 2016). "The link between TSC1/2 expression, mTORC1 activity and breast cancer metastatic potential was primarily investigated by analyzing publicly available gene expression datasets." (PMID 26167915, 2015). "Zinc finger protein CXXC5 promotes breast cancer by regulating TSC1/mTOR signaling pathway." (PMID 39717098, 2024). "It follows that TSC1 plays an important role in breast cancer." (PMID 37251941, 2023). "However, studies have reported that the level of TSC1/2 expression is lower in breast cancer and oral squamous cell carcinoma than in normal tissues." (PMID 37251941, 2023). "The hypermethylation of TSC1 promoters can be observed in breast cancer." (PMID 37251941, 2023). "Thus, upon mTOR inhibition, changes in AS events are maximized in the Tsc1-/- system compared to breast cancer cells." (PMID 36293270, 2022). "Over-expression of RPS6KB2 and EIF4EBP1 and under-expression of TSC1 might be indicators of more aggressive breast cancer phenotypes." (PMID 35608730, 2022). "Other potentially actionable mutations we identified were nonsynonymous mutations in PIK3CA and TSC1, also annotated in both COSMIC and OncoKB, and shown to be clinically targetable in breast cancer through PI3K inhibition and in central nervous system cancers with mTOR inhibition, respectively." (PMID 34464379, 2021). "Downregulation of the mTOR inhibitor TSC1 in effusion may lead to subsequent activation of mTORC1 at this site of metastasis, suggesting that this signaling pathway may be altered along tumor progression in breast carcinoma." (PMID 19680458, 2010). "We demonstrated that in breast cancer cells, CXXC5 is responsible for initiating the transcriptional repression of TSC1, followed by monoubiquitination of H2AK119 by the CRL4B complex and NuRD (MTA1) complex–mediated histone deacetylation, which create a repressive chromatin environment." (PMID 36539038, 2023). "Thus, lower expression of TSC1, along with higher expression of RPS6KB2 and EIF4EBP1, can be indicative of more aggressive breast cancer phenotypes." (PMID 35608730, 2022). "Based on these findings, we further found that the downregulation of DNA methylation of three CpG sites, TSC1 (cg14350545), FADD (cg02794589), and TRADD (cg05178604) could significantly prolong the survival of breast cancer patients (DNA methylation survival curves in the TCGA)." (PMID 33194583, 2020). "More recently, it has been shown that aberrant expression of TSC1 and TSC2 may be present in breast cancers, renal carcinoma, transitional cell carcinoma, basal cell carcinoma, squamous cell carcinoma and shagreen patches and may serve as a prognostic marker in breast cancer." (PMID 16412252, 2006). "As TSC1/TSC2 complex is an activator of mTORC2 signaling and a repressor of mTORC1 and Rheb is an activator of mTORC1 signaling, this data suggests that mTORC2 signaling may be more prominent in ERα+ and mTORC1 signaling may be more prevalent in ERα− breast carcinomas." (PMID 25283550, 2014).
breast carcinoma (continued). "Unexpectedly, the decreased NF1, TSC1, and TβRII expression did not clearly correlate with DMFS in the basal subtype of breast cancer patients." (PMID 38997291, 2024). "However the key components of the pathway, such as TSC1/TSC2 and mTORC1, have not been well investigated in normal mammary development, though their roles in breast cancer development have been known better." (PMID 26795955, 2016).
bladder cancer (29 papers, 2009 to 2024). "The low-risk group included 72% of the TSC1 mutation (28 of 39 TSC1 mutations) or 67% of the ERBB3 mutation (30 of 45 ERBB3 mutations) in bladder cancer." (PMID 37894365, 2023). "Rapamycin and its analogs, rapalogs, cause partial responses in about 10% of RCC patients, and have been reported to have major benefit in occasional cases of bladder cancer and other cancer types with TSC1/TSC2 mutations." (PMID 37909334, 2023). "Missense mutations of TSC1 found in bladder cancer were shown to cause loss of function through aberrant splicing, protein instability, or protein mislocalisation." (PMID 32842545, 2020). "Either the inactivation of PTEN and TSC1/2 or activation of mutations of PIK3CA are commonly observed in advanced bladder cancer and are associated with worse outcomes." (PMID 32414171, 2020). "Mutations of TSC1 have been identified in 14.5% of bladder tumors and loss of heterozygosity of TSC1 has been reported approximately 54% of bladder cancers." (PMID 31645902, 2019). "Mutation and inactivation of TSC1 in bladder cancer cells leads to decreased sensitivity to Hsp90 inhibitors." (PMID 31645902, 2019). "Mutation and inactivation of TSC1, such as those frequently observed in bladder cancer cells leads to hypoacetylation of Hsp90, enhanced ATPase activity, and reduced binding to inhibitors." (PMID 31645902, 2019). "Highly variable mutations of TSC1 have been previously identified in bladder cancer and correlate with sensitivity to the Hsp90 inhibitors." (PMID 31645902, 2019). "In this study we showed that mutation and loss of TSC1 in bladder cancer cells reduced the accumulation of Hsp90 inhibitors in these cells and decreased cell sensitivity to Hsp90 inhibitors." (PMID 31645902, 2019). "Mutation and inactivation of the tumor suppressor TSC1 has been found in approximately 15% of bladder cancers and loss of heterozygosity of a region spanning the TSC1 locus at 9q34 has been seen in roughly 54% of bladder cancers." (PMID 31645902, 2019). "Our results suggest that Tsc1 status can predict response to Hsp90 inhibition in bladder cancer patients and further provide a strategy to co-target HDACs and Hsp90 in bladder cancers with mutation in TSC1." (PMID 31645902, 2019). "This expression signature of TSC2 loss was increased in human bladder cancer with TSC1 or TSC2 mutation." (PMID 28695825, 2017). "A Tsc2/mTORC1 expression signature identified in Tsc2-deficient fibroblasts was also increased in bladder cancers with TSC1/TSC2 mutations in the TCGA database." (PMID 28695825, 2017). "Using the TCGA database of cancers, the TSC2 loss-of-function expression signature, as well as levels of LGALS3, were associated with bladder cancers harboring TSC1/TSC2 inactivating mutations." (PMID 28695825, 2017). "TSC1 inactivating mutations have been known in bladder cancer for many years, and this responding patient had a truncating mutation in TSC1." (PMID 26137524, 2015). "In this respect, a recent study among bladder cancer patients have reported that everolimus was more effective in patients with a somatic mutation in the TSC1 complex." (PMID 25962426, 2015). "Although Lkb1 was not previously linked with bladder cancer and very few Lkb1 mutations were found in human bladder cancer, this kinase is a known regulator of TSC1/2 complex via AMPK and subsequent suppression of mTOR." (PMID 21283818, 2011). "Our data supported this hypothesis, and we mechanistically demonstrated that mutation and loss of TSC1 in bladder cancer cells causes hypoacetylation of Hsp90-K407/K419 and subsequent decreased binding of Hsp90 to its inhibitor ganetespib." (PMID 31645902, 2019). "We therefore hypothesized that mutation and inactivation of TSC1 in bladder cancer cells leads to decreased sensitivity to Hsp90 inhibitors." (PMID 31645902, 2019).
bladder cancer (continued). "Additionally, in those patients with TSC1 mutated bladder cancer, inhibition of HDACs can potentially restore Hsp90 acetylation and sensitivity to Hsp90 inhibitors." (PMID 31645902, 2019). "However, increasing Hsp90 acetylation through HDAC inhibition with ACY-241 resulted in enhanced Hsp90 inhibitor binding as well as sensitization to Hsp90 inhibitors in the TSC1 mutated RT4 bladder cancer cell line." (PMID 31645902, 2019). "Bladder cancers with mutations in TSC1 or TSC2 also had higher levels of galectin-3, suggesting that other diseases linked with mutations in these genes may also result in increased production of galectin-3." (PMID 28695825, 2017). ", suggesting that Gal-3 may be an individual marker for bladder cancers containing inactivating mutations in TSC1 or TSC2." (PMID 28695825, 2017). "However, recent studies of TSC1 missense variants identified in bladder cancers and in patients with TSC have shown that TSC1 amino acid substitutions can be pathogenic, reducing steady state levels of TSC1 and leading to increased mTOR activity." (PMID 19747374, 2009). "Interestingly, approximately 15% of bladder cancers have loss-of-function mutations in Tsc1." (PMID 35883484, 2022). "In bladder cancer cells, TSC1 facilitated Hsp90 acetylation at K407/K419, which increased its binding affinity for Hsp90 inhibitor ganetespib." (PMID 36008939, 2022). "In contrast to bladder cancer cells, however, CAL-72 and PEER cells, which have a complete loss of TSC1 and reduced TSC2 expression, were also sensitized to ganetespib with IC50 values of 22 and 3 nM, respectively." (PMID 36008939, 2022). "Combined Hsp90/mTOR (mammalian target of rapamycin) inhibition is a promising therapeutic approach for TSC1-mutant bladder cancer." (PMID 32842545, 2020). "We therefore treated the bladder cancer cells with a pan-HDAC inhibitor with the goal of restoring Hsp90 acetylation in Tsc1-mutant cells and subsequent sensitivity to Hsp90 inhibitors." (PMID 31645902, 2019). "In particular, the co-occurrence of TSC1 and PIK3CA or PTEN mutations has been reported in bladder cancer." (PMID 31258848, 2019). "Pharmacologic inhibition of histone deacetylases (HDACs) restores acetylation of Hsp90 and sensitizes Tsc1-mutant bladder cancer cells to ganetespib, resulting in apoptosis." (PMID 31645902, 2019). "Taken together, these data show that presence of Tsc1 enhances bladder cancer cell sensitivity and uptake of Hsp90 inhibitors." (PMID 31645902, 2019). "Overall, our data provide evidence that inhibition of HDACs in bladder cancer cells that lack Tsc1 provides a strategy to enhance the efficacy of Hsp90 inhibitors." (PMID 31645902, 2019). "Our data showed that Hsp90 binding was significantly reduced in TSC1 mutated RT4 cells compared to TSC1 WT T24 and UM-UC-3 bladder cancer cells." (PMID 31645902, 2019). "Mutations in genes concurrently with TSC1/TSC2, such as those frequently occurring in bladder cancers, will likely define the best treatment course." (PMID 28695825, 2017). "TSC1 forms a complex with TSC2 and its mutations were found in a number of bladder cancer cases as well." (PMID 21283818, 2011). "AKT/PI3K/mTOR pathway alterations are very frequent in bladder cancer, with 73% of human bladder tumours characterised by alterations in one of the major pathway components: TSC1, PI3K (PIK3CA) or PTEN." (PMID 21283818, 2011). "Lkb1 kinase is a tumour suppressor which regulates the TSC1/2 complex, which is often deregulated in human bladder cancer." (PMID 21283818, 2011).
bladder cancer (continued). "This network module contains the known bladder cancer driver TSC1 (and 9 other-known cancer drivers) and 5 putative bladder cancer drivers one of which is RXRA, whose mutation activates the peroxisome proliferator-activated receptors, which switch on genes driving cell proliferation." (PMID 35035776, 2022). "Deficient TSC1 or TSC2 is also observed in hepatocellular carcinoma (HCC) and bladder cancer." (PMID 35805935, 2022). "Mutations of TSC1 (tuberous sclerosis 1, 9q34) are found in 10–15% of bladder cancers with no clear association with grade or stage." (PMID 32842545, 2020). "In bladder cancer, it was shown that up to 40% of cases had genetic alterations in components of the PI3K/AKT/mTOR pathway, including PTEN deletions and activating mutations for TSC-1, PIK3CA, and AKT." (PMID 32414171, 2020). "Our findings suggest that TSC1 status may predict response to Hsp90 inhibitors in patients with bladder cancer, and co-targeting HDACs can sensitize tumors with Tsc1 mutations to Hsp90 inhibitors." (PMID 31645902, 2019). "In addition to the effect on inhibitor accumulation, TSC1 expression also significantly sensitized RT4 bladder cancer cells to Hsp90 inhibitor as evidenced by WST proliferation assay." (PMID 31645902, 2019). "Previous reports investigating PI3K pathway inhibition in bladder cancer have demonstrated that cells possessing activating mutations in PIK3CA are selectively sensitive to PI3K or AKT inhibition, while TSC1 or mTOR mutations contribute to sensitivity to rapalogs." (PMID 29357370, 2018). "Why Lkb1 sporadic mutations are not common in human bladder cancer is an outstanding question considering both our findings as well as its known function in regulating TSC1/2 complex." (PMID 21283818, 2011). "This suggests that TSC1 status may predict sensitivity to Hsp90 inhibitors in bladder cancer." (PMID 31645902, 2019). "Conversely, re-expression of WT Tsc1 in RT4 cells restored uptake and retention of ganetespib in these bladder cancer cells." (PMID 31645902, 2019). "We have further demonstrated that presence of Tsc1 facilitates accumulation of fluorescently-tagged Hsp90 inhibitor, BODIPY-ganetespib, in bladder cancer cells after 4 hours of treatment." (PMID 31645902, 2019). "The panel of cell lines included in our study possesses diverse molecular alterations in FGFR3, RAS, PIK3CA, PTEN, TSC1 and mTOR that are capable of influencing response to PI3K pathway inhibition and are very frequent in bladder cancer specimen." (PMID 29357370, 2018). "Similarly, bladder cancer cells lacking functional Tsc1 fail to accumulate Hsp90 inhibitors and are less sensitive to Hsp90 inhibition than those with wild-type Tsc1." (PMID 35883484, 2022). "Mutation or absence of TSC1 led to hypoacetylation of Hsp90 and this was demonstrated in Hsp90 isolated from four cell types lacking TSC1: 1) bladder cancer cells with TSC1 mutation, 2) TSC1 KO HAP1 cells, 3) conditional knockout of TSC1 in mouse brain and 4) TSC1 KO MEFs." (PMID 31645902, 2019).